GOLGA6L7 (golgin A6 family like 7)
Synonyms: GOLGA6L7P
Gene: Protein-coding gene on chromosome 15 (28,841,832 to 28,848,675, reverse strand). Ensembl gene ENSG00000261649.
Gene Ontology:
Cellular component: cis-Golgi network; Golgi apparatus
Genetic constraint (gnomAD): Loss-of-function variants: 13 observed, 23.16 expected, observed/expected ratio (o/e) 0.56, 90% interval 0.36 to 0.89. The synonymous counts are far from expectation, so gnomAD's model fits this gene poorly and the ratio says little. Missense variants: 126 observed, 176.32 expected, observed/expected ratio (o/e) 0.71, 90% interval 0.62 to 0.83. Synonymous variants: 27 observed, 54.09 expected, observed/expected ratio (o/e) 0.5, 90% interval 0.37 to 0.69.
Homologues: Paralogues in human: GOLGA6L2 (53% identical), GOLGA6L22 (48% identical), GOLGA6L6 (48% identical), GOLGA6L25 (47% identical), GOLGA6L24 (47% identical), GOLGA6L26 (45% identical), GOLGA6L1 (44% identical), GOLGA6L4 (22% identical), GOLGA6L10 (20% identical), GOLGA6L9 (20% identical).